IRF5 (interferon regulatory factor 5)
Diseases named in the same sentence as IRF5 in open-access papers (continued):
Sharing a sentence is not in itself a finding about the gene and the disease.
influenza (8 papers, 2011 to 2025). An acute viral infection of the respiratory tract, occurring in isolated cases, in epidemics, or in pandemics; it is caused by serologically different strains of viruses (influenzaviruses) designated A, B, and C, has a 3-day incubation period, and usually lasts for 3 to 10 days. "Factors associated with anti-vital immunity, such as IRF5 (identified in our study) were found to be part of a molecular signature induced by LAIV influenza vaccination." (PMID 38633249, 2024). "This highlights a molecular mechanism by which HBP-mediated O-GlcNAcylation regulates IRF5 function during influenza infection and underscores the vital role of glucose metabolism in influenza-induced cytokine storm." (PMID 41511331, 2025). "Here, we provide novel data showing that the transcription factor Interferon regulatory factor 5 (IRF5) controls cellular and metabolic responses to influenza infection and TLR3 activation in vivo." (PMID 33423291, 2021). "Similar to that observed in the circulation of influenza-vaccinated healthy donors, increased IRF5 expression was detected in B cells over the 7-day in vitro culture period." (PMID 29367853, 2017). "STAT1 and the JAK/STAT signaling pathway is known to be targeted by influenza virus, but IRF2 and IRF5 have not been demonstrated to play a role in response to influenza infection previously and thus represent novel predictions for further experimental investigation." (PMID 22074594, 2011). "Given that IFN-stimulated genes contribute to anti-influenza immunity, to identify whether IFR5 and/or related pathways could be safely exploited to dampen inflammatory cytokine responses to influenza virus, it is important to understand the relationship between IRF5 and virus-induced type 1 IFN." (PMID 32075938, 2020).
lupus nephritis (8 papers, 2010 to 2025). Glomerulonephritis in the context of systemic lupus erythematosus. "In this study, we evaluate the variants on three genes STAT4, CDKN1A, and IRF5 and their association with lupus nephritis." (PMID 33687153, 2021). "Thus, in this report, we evaluate the polymorphisms of these three genes (STAT4, CDKN1A and IRF5) and their association with the phenotype of patients with Lupus nephritis." (PMID 33687153, 2021). "IRF5 genotype distribution at three sites, namely, SNP rs6953165, rs2004640, and rs41298401 between patients with lupus nephritis and the control group was similar." (PMID 33687153, 2021). "Inhibition of IRF5 hyperactivation in a mouse model of SLE protected from lupus nephritis onset and severity, and improved kidney function and pathology." (PMID 34887417, 2021). "Strong signals of association between IRF5 and an HLA-DR3 SNP marker were also detected in the lupus nephritis case versus healthy control analysis (p <0.0001)." (PMID 24386384, 2013). "The aim of this study was to compare genetic variants from the TGFB1, IRF5, STAT4 genes and TRAF1-C5 locus with susceptibility to IgAN and lupus nephritis in two Swedish cohorts." (PMID 20479942, 2010). "For instance, our term-driven analysis highlights IRF5 and STAT4 as pivotal genes linking proteinuria and skin rash in lupus nephritis (LN)." (PMID 40128671, 2025). "In addition, decreased miR-146a may result in upregulation of interferon regulatory factor 5 (IRF-5) and then enhanced production of IFN-α, STAT-1, IL-1 receptor associated kinase-1 (IRAK1), and TRAF6, which then increase innate immune responses, lupus disease activity, and lupus nephritis." (PMID 31635056, 2019).
hepatocellular carcinoma (7 papers, 2011 to 2025). A malignant tumor that arises from hepatocytes. "It is reported that in hepatocellular carcinoma and gastric cancer, IRF5 expression is down-regulated due to gene promoter hyper-methylation." (PMID 28562332, 2017). "It has recently been demonstrated that the IRF5 promoter is frequently hypermethylated in hepatocellular carcinoma tissue samples." (PMID 22053985, 2011). "To determine whether IRF5′s control over cell migration is specific to mammary epithelial cells, we examined IRF5-mediated migration in three other epithelial cancer cell types - PANC1 human pancreatic carcinoma cells, HT29 human colon adenocarcinoma cells, and Huh 7.5 human hepatic carcinoma cells." (PMID 25649192, 2015).
ZIKV infection (7 papers, 2017 to 2022). "Previous work has demonstrated that wild-type immunocompetent mice are resistant to ZIKV pathogenesis but that mice lacking alpha/beta interferon (IFN-α/β) signaling (e.g., Ifnar1−/−, A129, AG129, Irf3−/− × Irf5−/− × Irf7−/−) succumb to ZIKV infection." (PMID 28270583, 2017). "We evaluated the crosstalk between RIG-I and DNA-PKcs during ZIKV infection analyzing the IFN-I/III-inducing transcription factors including IRF1, IRF3, IRF5, IRF7, and p65 (NF-κB subunit)." (PMID 36311766, 2022). "We observed that ZIKV infection induces IRF1 and IRF3, but not IRF5 and IRF7 nuclear accumulation." (PMID 36311766, 2022).
gastric cancer (6 papers, 2017 to 2025). A primary or metastatic malignant neoplasm involving the stomach. "A previous study showed that EBV-induced promoter methylation and repression of IRF5 transcription are linked to gastric carcinoma development." (PMID 29438328, 2018). "Hypomethylation of CpG islands in the interferon regulatory factor 5 (IRF-5) promoter was observed in EBV type III latent infected Burkitt’s lymphoma and gastric carcinoma cell lines to restrain IFR5 expression." (PMID 35335337, 2022). "Interferon regulatory factor 5 (IRF5), which mediates virus-induced innate immune responses via toll-like receptors (TLRs), has also been observed to be hypermethylated in EBV-positive gastric cancer cell lines and EBVaGC tissues." (PMID 34956172, 2021).
heart failure (6 papers, 2016 to 2024). Inability of the heart to pump blood at an adequate rate to meet tissue metabolic requirements. "In this regard, silencing of interferon regulatory factor 5 (IRF5), which regulates polarization toward the M1 phenotype, shifted macrophage phenotype from M1 to M2 in the heart and attenuated heart failure post-MI." (PMID 31632398, 2019). "The progression of heart failure can be attenuated through a suppression of interferon regulatory factor 5 (IRF5), a crucial transcription factor in cardiac macrophages, which is downregulated in M1 cardiac macrophages." (PMID 30523422, 2018). "Silencing IRF5 improves infarct healing and attenuates heart failure via accelerated resolution of inflammation in the mouse MI model." (PMID 30397194, 2018). "Previously, we reported that 4F, an apoA-I mimetic, reduced myocardial inflammation and fibrosis and heart failure in Tsk/+ mice by a mechanism that appeared to be mediated in part, by the ability of 4F to bind IRF5." (PMID 27050551, 2016). "As 4F possesses many mechanisms of action, its ability to prevent myocardial inflammation and heart failure in Tsk/+ mice cannot be attributed exclusively to its ability to inhibit IRF5." (PMID 27050551, 2016).
Hepatic fibrosis (6 papers, 2017 to 2024). The presence of excessive fibrous connective tissue in the liver. "IRF5 also plays a role in liver fibrosis caused by hepatitis C virus or in non-alcoholic fatty liver disease." (PMID 30515152, 2018). "Our data on the effective reduction in M1 polarization markers NOS2, Il6, and TNF-α make siRNA to IRF5 a strong candidate for in vivo modulation of liver fibrosis." (PMID 36010574, 2022). "IRF5 expression was significantly higher in liver macrophages from human subjects with liver fibrosis than healthy controls and its expression positively correlated with clinical markers of liver damage." (PMID 30515152, 2018). "Interestingly, mice lacking IRF5 in myeloid cells were found to be protected from stress-induced hepatic fibrosis, suggesting the crucial role of IRF5 in hepatocellular cell death and liver fibrosis in both mice and humans." (PMID 38999981, 2024). "Since IRF5 mediates hepatocyte death and liver fibrosis in mice as well as humans, modulation of IRF5 function may be another attractive approach to treat fibrosis." (PMID 34064375, 2021). "Conversely, IRF5-deficient macrophages under hepatocyte stress exhibited immunosuppressive polarization, secreting IL-10 and TGFβ to support BCL2 family member-mediated anti-apoptotic signaling in hepatocytes during metabolic or toxic stress-induced liver fibrosis." (PMID 38999981, 2024). "In human hepatocyte macrophages with liver fibrosis from NAFLD or HCV infection, elevated IRF5 expression triggered the release of inflammatory cytokines and death effectors, leading to hepatocyte caspase-dependent apoptosis." (PMID 38999981, 2024). "Additionally, it was shown that mice lacking IRF5 in myeloid cells demonstrated reduced hepatic fibrosis in the acute CCl4 toxic model and in the nonalcoholic steatosis model (NASH)." (PMID 36010574, 2022). "Of note, mice lacking Irf5 in their myeloid compartment were protected from hepatic fibrosis." (PMID 30515152, 2018). "Interferon regulatory factor 5 (IRF5) has emerged as an important pro-inflammatory transcription factor involved in macrophage-mediated liver fibrosis and is a marker of liver damage Mice lacking IRF5 are protected from hepatic fibrosis induced by metabolic or toxic stress." (PMID 34064375, 2021).
lung carcinoma (6 papers, 2011 to 2024). "To elucidate the impact of IRF5 M1‐exos on lung cancer cells, we conducted coculture experiments with the A549 or SPC‐A1 cell lines using PBS, M1‐exos, and IRF5 M1‐exos." (PMID 39623605, 2024). "Collectively, these findings conclusively demonstrate that IRF5 M1‐exos possess inhibitory effects on lung cancer cell survival and proliferation while attenuating cellular migration and invasion capabilities, thereby impeding tumorigenesis." (PMID 39623605, 2024). "Coculturing M1‐exos or si‐IRF5 M1‐exos with lung cancer cells from both Vector and OE‐HLA‐E groups demonstrated that overexpression of HLA‐E led to decreased metabolic activity and viability of A549 and SPC‐A1 cells, irrespective of coculture conditions." (PMID 39623605, 2024). "Although our study provides significant insights into the role of IRF5 and HLA‐E in lung cancer treatment, there are still certain limitations." (PMID 39623605, 2024). "Our findings demonstrate that, similar to M1‐exos, IRF5 M1‐exos significantly impedes the survival and proliferation of lung cancer cells while attenuating their migratory and invasive capabilities." (PMID 39623605, 2024). "Western blot analysis revealed an increase in HLA‐E protein expression in the M1‐exos group compared to the PBS group, and lung cancer cells cocultured with IRF5 M1‐exos exhibited higher levels of HLA‐E expression." (PMID 39623605, 2024). "Further investigations are warranted to explore the therapeutic potential of IRF5 and HLA‐E in lung cancer treatment." (PMID 39623605, 2024). "Next, we further investigated the potential involvement of HLA‐E in the growth of lung cancer cells mediated by IRF5." (PMID 39623605, 2024). "Collectively, these findings suggest that IRF5 regulates lung cancer cell growth through its interaction with HLA‐E, wherein overexpression of HLA‐E can counteract the tumor‐promoting effects induced by si‐IRF5 M1‐exos." (PMID 39623605, 2024). "The effect of IRF5 M1‐exos on the proliferation and metastasis of lung cancer cells were observed through in vitro coculturing with lung cancer cells." (PMID 39623605, 2024). "In conclusion, our study reveals the potential role of IRF5 derived from M1‐like macrophage exosomes in lung cancer treatment through the upregulation of HLA‐E expression, thus providing a novel theoretical foundation for future immunotherapy strategies." (PMID 39623605, 2024). "In this study, we developed an engineered M1‐like macrophage exosomes expressing IRF5 (IRF5 M1‐exos) and demonstrated their ability to inhibit proliferation, migration, and invasion of lung cancer cells." (PMID 39623605, 2024). "Altogether the selective loss of viral protection in lung cancer cells was related to epigenetic inactivation of at least one of the IRFs implicating the necessity of both IRF7 and IRF5 to be active for a functional IFN pathway." (PMID 22194884, 2011). "Bisulfite sequencing revealed promoter hypermethylation of either IRF7 and/or IRF5 in several lung cancer cell lines." (PMID 22194884, 2011). "The disruption of the IFN pathway in lung cancer cell lines and primary tumor tissues is caused by epigenetic silencing of critical interferon responsive transcription factors IRF7 and/or IRF5." (PMID 22194884, 2011). "Since IRF5 induced a stronger transcription profile of the early antiviral genes and has been newly identified as a novel methylation marker for cancer, we further examined the methylation status of IRF5 promoter regions in lung cancer cells." (PMID 22194884, 2011). "Furthermore, we validated the role of HLA‐E in regulating lung cancer growth mediated by IRF5 M1‐exos." (PMID 39623605, 2024). "We investigated the impact of IRF5 M1‐exos on lung cancer cell proliferation and tumor growth and, for the first time, identified that alterations in IRF5 expression result in significant upregulation of HLA‐E expression and promoter activity in lung cancer cell lines." (PMID 39623605, 2024).
lung carcinoma (continued). "Given that HLA‐E is a downstream target gene of IRF5, we speculated that HLA‐E may be involved in the regulation of lung cancer cell growth by IRF5." (PMID 39623605, 2024). "Despite limited research on the correlation between IRF5 and HLA‐E in human lung cancer, it is hypothesized that IRF5 could play a crucial role in regulating HLA‐E expression." (PMID 39623605, 2024). "Furthermore, in mouse models of lung cancer, the administration of IRF5 M1‐exos effectively suppressed tumor growth, surpassing the anticancer effects observed with conventional M1‐exos." (PMID 39623605, 2024). "Although basal levels of most ISGs were reduced in all the lung cancer cell lines compared to normal bronchial epithelial cells, oncolytic viral sensitivity is only associated with polyI:C-inducible expression levels of certain key ISGs such as IRF7 and IRF5." (PMID 22194884, 2011). "Moreover, transcription factors IRF5 and IRF7 were identified as critical regulators of innate immune system and useful biomarkers for oncolytic virus susceptibility in lung cancer cells as both of them have to be inducible for a functional IFN pathway." (PMID 22194884, 2011). "Therefore, IRF5 M1‐exos represent an attractive therapeutic strategy for lung cancer." (PMID 39623605, 2024). "Therefore, increasing the content of IRF5 in M1 macrophage exosomes may enhance its antitumor effect, offering a potential future treatment for lung cancer." (PMID 39623605, 2024). "For example, genes such as IRF5 and STAT1 are downregulated in lung cancer cells after infection by viral RNA29, similar to PDX tumor groups with high murine virus load in our analyses." (PMID 33795676, 2021). "Consistently, USP17 expression in lung cancer cells enhanced basal and stimuli-induced inflammatory responses by stabilizing NIK, c-Rel, and IRF5 through disrupting the TRAF2/TRAF3 complex." (PMID 30038267, 2018). "We presented evidence that functional inactivation of IRF5 and IRF7 is the major mechanism to disrupt IFN signaling in lung cancer cells." (PMID 22194884, 2011). "We have shown epigenetic silencing of IRF5 and IRF7 at CpG islands of promoter regions in lung cancer." (PMID 22194884, 2011). "Notably, the mechanism by which IRF5 exerts its antitumor function through HLA‐E regulation in lung cancer has not been fully elucidated." (PMID 39623605, 2024). "A strong polyI:C-induction of phosphorylated-STAT1 (p-STAT1, Ser727), STAT1, IRF5 and IRF7 protein levels was consistent with the resistance of normal Beas2B cells and the two cancer cells, HTB182 and CRL5928, to VSV infection and vice versa for the viral-sensitive lung cancer cell line." (PMID 22194884, 2011). "Therefore the methylation IRF7 or IRF5 promoters found in the lung cancer cell lines probably had its origin in the tumor rather than being an event selected during to cell culture." (PMID 22194884, 2011). "However 5-aza-dC treatment failed to reactivate IRF5 or IRF7 expression or rescue lung cancer cells from VSV infection." (PMID 22194884, 2011). "Similarly, when we investigated DNA from fresh frozen lung cancer tissues, we observed promoter methylation of IRF7 and/or IRF5, suggesting that their IFN antiviral response was also epigenetically silenced as functional IRF7 and IRF5 are required for an intact IFN pathway." (PMID 22194884, 2011). "Therefore, IRF5 and IRF7 are key transcription factors in IFN pathway that determine viral sensitivity of lung cancer cells; the epigenetically impaired IFN pathway in lung cancer tissues provides potential biomarkers for successful selective killing of cancer cells by oncolytic viral therapy." (PMID 22194884, 2011). "IRF5 and IRF7 protein levels were uniformly not inducible upon polyI:C treatment in all the virus-sensitive lung cancer cell lines." (PMID 22194884, 2011).
ulcerative colitis (6 papers, 2012 to 2025). An inflammatory bowel disease involving the mucosal surface of the large intestine and rectum. "Interestingly, rs4728142 is also associated with ulcerative colitis (UC) where both IRF5 and TNPO3 are reported as candidate genes." (PMID 22685416, 2012). "IRF5 plays a key role in the inflammatory response and is believed to contribute to the pathogenesis of ulcerative colitis (UC) through multiple mechanisms." (PMID 41007813, 2025).
glioblastoma (5 papers, 2019 to 2024). The most malignant astrocytic tumor (WHO grade IV). "Remarkably, E2F5 was significantly correlated with M1 macrophage markers (IRF5) and monocyte markers (CD115), suggesting that it plays a role in regulating monocyte polarization in glioblastoma." (PMID 36979479, 2023).